KEAP1 (kelch like ECH associated protein 1)
Diseases named in the same sentence as KEAP1 in open-access papers (continued):
Sharing a sentence is not in itself a finding about the gene and the disease.
cancer (continued). "Mutations in NFE2L2 exon 2 were already described as a common mechanism of NRF2 hyper‐activation in cancer because alterations in this exon lead to an aberrant Neh2 domain and consequently to NRF2 stabilization in the cytoplasm by escaping KEAP1‐regulated degradation." (PMID 39707614, 2025). "The docking results of caffeic acid (CA) and benzyl isothiocyanate (BITC) with key cancer-related receptor proteins—including ERK2 (PDB: 4QTB), p38 MAPK (PDB: 3GCU), Bcl-2 (PDB: 4MAN), Keap1-Nrf2 complex (PDB: 5YWE), and GST (PDB: 1ZHA)—revealed strong binding interactions." (PMID 40799801, 2025). "We have identified a plausible, macrophage-related biological regulation by which the immune microenvironment can be reinvigorated, regardless of the cancer’s KEAP1 status." (PMID 41462606, 2025). "In these cell lines, KYNU was upregulated even in the absence of KEAP1/STK11 co-mutation, indicating that KYNU regulation varies across cancer lineages." (PMID 40427178, 2025). "Moreover, the redox-sensitive nature of KEAP1 influences its interaction with PGAM5, potentially affecting the balance between cell survival and death in response to oxidative stress and cancer therapies." (PMID 39941813, 2025). "Furthermore, our analysis identified three ferroptosis‐related genes, including IFNG, KEAP1, and PHKG2, as key biomarkers in prognosis prediction and potential targets for OV cancer therapy." (PMID 40744688, 2025). "Both KEAP1-KO and WT cancer cells were successfully engrafted into the albino C57BL/6 mice, and the KEAP1-KO tumors displayed moderately accelerated growth compared to WT tumors, suggesting that the NRF2 activation in 3LL cells by the KEAP1 deletion promotes the cancer cell growth." (PMID 41035689, 2025). "Furthermore, PTMA’s ability to modulate KEAP1 and NRF2 pathway positions it as a potential target for therapeutic strategies aimed at manipulating these interactions to combat cancer progression." (PMID 39941813, 2025). "KEAP1 is the regulator upstream of the well-known oxidative and electrophilic stress defender NRF2, and the KEAP1-NRF2 pathway works as the oncogenic signaling to provide survival advantage to cancer cells after activation." (PMID 40611261, 2025). "Although no KEAP1 agonists are currently in clinical development or application, our results underscore KEAP1 as a promising target for cancer immune checkpoint blockade therapy." (PMID 38413563, 2024). "Leveraging the KEGG database, we identified signaling pathways associated with KEAP1, with particular emphasis on the negative association with the PI3K-AKT signaling pathway, a widely recognized promoter of cancer." (PMID 38413563, 2024). "Generally, we observed great homology between the KEAP1 KO cells and hypothesize some of the differences observed are the result of biological variability between cells of the LL2 WT cancer line used for their generation." (PMID 38542481, 2024). "Considering that KEAP1 may participate in cell development and signal transduction from the results of GO and GSEA, and the important role of cellular immunity in cancer progression." (PMID 38938386, 2024). "However, in RCC, the constitutive activation of Nrf2, resulting from modifications of the KEAP1–Nrf2-CUL3 complex, enhances cancer cell proliferation, survival, metastatic potential, and resistance to therapies." (PMID 39769005, 2024). "Studies have shown that aberrant activation of NRF2 in cancer can promote cell proliferation, the NRF2/KEAP1 signaling pathway is significant for the regulation of autophagy and the immune system, meanwhile, it is involved in tumorigenesis by regulating metabolic reprogramming." (PMID 38245763, 2024). "Here, using immunodeficient and immunocompetent orthotopic murine cancer models, we demonstrate that DRP-104, a broad-acting glutamine antagonist, is efficacious against KEAP1 mutant tumors by a mechanism distinct from GLS1-selective inhibitors, such as CB-839." (PMID 38536921, 2024).
cancer (continued). "Our study uncovered a novel KEAP1-independent mechanism for NRF2 activation, suggesting the theoretical feasibility of developing a drug targeting NSUN2 to reduce the overall m5C level and malignant phenotype of cancer cells." (PMID 38403250, 2024). "Cancer cells manage levels of H2O2 through multiple antioxidant enzyme systems, and under sustained oxidative stress will transcriptionally upregulate several antioxidant enzymes via the Keap1-Nrf2 axis." (PMID 36978989, 2023). "In addition, USP15 stabilizes KEAP1 and promotes the degradation of NRF2, leading to the sensitization of cancer cells to chemotherapy." (PMID 36694209, 2023). "The KEAP1-nuclear factor erythroid-derived 2-like 2 (NRF2) pathway plays a crucial role in regulating the cellular response to oxidative stress, and its signaling abnormalities have been observed in various cancer types, including NSCLC." (PMID 37675220, 2023). "Furthermore, in the cancer signalling pathway, Nrf2 is also regulated by phosphoinositide 3-kinase (PI3K) independently of Keap1." (PMID 37841775, 2023). "Apart from KEAP1, another E3 ligase, β-TrCP also participates in the degradation of NRF2, whose downregulation is closely related to drug resistance in various types of cancer." (PMID 36694209, 2023). "This study evaluated survival benefit with different 1L and 2L therapies in patients with KRAS G12C or WT cancer with or without STK11 and/or KEAP1 mutations, providing additional insights into these frequently co-occurring mutations." (PMID 37069542, 2023). "Metformin has been found to activate Nrf2/Keap1 signaling in neurons, the liver, and skeletal muscle in an AMPK-dependent manner however, it has also been found to inhibit Nrf2 and reverse chemoresistance in various cancer cell lines." (PMID 37760031, 2023). "Interestingly, the suppression of miR-141-3p by circKEAP1 increases KEAP1 protein levels, which decreases the NRF2 protein level and inhibits cancer growth." (PMID 37511619, 2023). "The KEAP1-Nrf2/ARE pathway is a pivotal cytoprotective regulator against oxidative stress which plays an important role in the development of many inflammatory diseases and cancer." (PMID 37351768, 2023). "Furthermore, sequestration of KEAP1 by NRF2-competitive-binding proteins including TRIM21, RPRD1A, and FAM129B was found in NRF2-addicted cancer models 9-11." (PMID 36632216, 2023). "Thereby, our experimental evidence further revealing that two isoforms of Keap1 (α and β) could still inhibit the expression of Nrf2 and its target genes HO-1 and NQO-1 in cancer cells." (PMID 36142252, 2022). "However, the expressions of CUL3, GSK3B, KEAP1, and MAPK9 showed positive relationship with RNAss in various cancers." (PMID 35242279, 2022). "In addition, we found a significant positive correlation between KEAP1 and BRD4 at the mRNA level in most cancer types." (PMID 35453346, 2022). "Additionally, exploration of miRNAs that are able to target KEAP1 will ay improve our knowledge of the NRF2/KEAP1 axis in all aspects of cellular biology, and especially in the field of oxidative stress and cancer, including its therapy response." (PMID 35268568, 2022). "To explore whether the restoration of Keap1 in Keap1-mutant cells affects cancer cell growth, we established a clone of SSC9 cells that stably express Keap1 cDNA." (PMID 35945195, 2022). "Under oxidative stress, the specific cysteine residues of KEAP1 in the KEAP1-CUL3-RBX1 complex are destroyed, thus interfering with the ubiquitination process of Nrf2, which may ultimately lead to cancer drug tolerance." (PMID 36245983, 2022).
cancer (continued). "Given that BRD4 is frequently elevated in cancer cells compared to normal cells, co-targeting of BRD4 and the KEAP1-Nrf2-G6PD axis might not only maximize the clinical efficacy of BET inhibitors but also cause fewer side effects in patients." (PMID 35453346, 2022). "This correlation suggests that the regulatory mechanism of BRD4 on KEAP1 and G6PD may be beyond SCLC and may exist in a variety of cancers which provides a new basis for overcoming drug resistance to BETis in other cancer types." (PMID 35453346, 2022). "Experiments on multiple cancer cell lines showed that brusatol can cooperate with multiple anti-cancer drugs to inhibit Nrf2 activity regardless of the presence of the Keap1 gene." (PMID 36267094, 2022). "Consequently, high levels of MnHex in cancer cells/tumors, along with high H2O2 levels, seem to be sufficient to oxidize Keap1 and activate NRF2 (see Introduction for details on the mechanism of protein oxidation by MnPs)." (PMID 34829640, 2021). "Flavonoids are known to activate the Keap1/Nrf2/ARE pathway and contribute to cytoprotection in normal cells; however, some flavonoids such as flavones, luteolin, apigenin, and chrysin are shown to inhibit Keap1/Nrf2/ARE and are proapoptotic in cancer cells." (PMID 34257824, 2021). "In this review, we provide an overview of the regulatory molecular mechanism of the NRF2/KEAP1 pathway against metabolic reprogramming in cancer, suggesting that the regulation of NRF2/KEAP1 axis might approach as a novel therapeutic strategy for cancers." (PMID 33922165, 2021). "Anti-cancer effects involve many mechanisms, including oxidative stress, intrinsic and extrinsic mechanisms, as well as the survivin, PI3K/Akt/mTOR, SHH, Nrf2/Keap1, inflammation, and autophagy pathways." (PMID 34863080, 2021). "In this review, we will describe how this signaling pathway works in physiological conditions and summarize the most important findings related to the role of NRF2/KEAP1 in LUAD and LUSC, focusing on their activation mechanisms and their implications in the progression of cancer." (PMID 34440648, 2021). "Intriguingly, not all mutations in KEAP1 reside at this interface and the missense mutation most frequently documented in KEAP1 in the COSMIC cancer database is R470C, which is curiously located distantly from the NRF2 binding site." (PMID 34065616, 2021). "In addition to the constitutive activation of Nrf2 by Keap1 deletion, DEM-induced Nrf2 activation was sufficient to sensitize cancer cells to glutaminase inhibition." (PMID 33672789, 2021). "A gene expression biomarker was built from statistically-filtered gene lists derived from microarray experiments in primary human hepatocytes and cancer cell lines exposed to NRF2-activating chemicals (oltipraz, sulforaphane, CDDO-Im) or in which the NRF2 suppressor Keap1 was knocked down by siRNA." (PMID 32986742, 2020). "In this regard, it is interesting to note that K67, a small noncovalent inhibitor of phospho-p62/Keap1 interaction, which thus increases Keap1-induced Nrf2 degradation, showed an antineoplastic effect in HCC cell lines by decreasing proliferation and enhancing cytotoxicity of anti-cancer drugs." (PMID 33053665, 2020). "The lowest correlation genetic interaction was observed between ATF4 and KEAP1, which is not entirely surprising considering KEAP1 has been reported to negatively regulate ATF4 expression in other cancer models." (PMID 33184288, 2020). "Similarly, the generated Keap1 and/or CUL3 mutants in cancer cells prevent CUL3–Keap1–Nrf2 complex formation, blocking Nrf2 ubiquitination." (PMID 33050575, 2020). "Although Keap1 promoter hypermethylation, negatively controlling gene expression, has been found in several cancers, not much is known about HCC." (PMID 32824383, 2020). "KEAP1, DNM2, SMARCA4 were annotated as tumor suppressor genes in the Cancer Gene Census database." (PMID 32337068, 2020).
cancer (continued). "Moreover, we will discuss the regulation of the KEAP1/NRF2 axis by metabolic perturbations and how this regulation also plays important roles in cancer." (PMID 33080927, 2020). "As there seems to be a selective advantage to inactivate KEAP1 in the presence of sorafenib, the absence of KEAP1 is expected to confer increased proliferation or survival of HUH-7 cancer cells exposed to sorafenib." (PMID 31903165, 2019). "Still, it could be interesting in future investigations to determine more precisely the importance of FaOH and FaDOH in the detoxification of chemical carcinogens via the Keap1/Nrf2/ARE pathway and their overall cancer preventive role." (PMID 31540047, 2019). "Since therapeutic targeting of NRF2 is not practical regulating KEAP1 has the potential to inhibit cancer-specific NRF2 signaling without affecting normal cells." (PMID 31288436, 2019). "To understand the differential effect of DMF on NRF2 activation in cancer and non-tumorigenic cells, we assessed the expression of KEAP1 and DJ-1 proteins, two partners of NRF2 that are targeted by DMF." (PMID 29507676, 2018). "In contrast to KEAP1, which we identified as novel target, mTOR has been suggested also by others based on the PI3K/mTOR pathway as the most frequently activated cascade for cancer initiation and progression." (PMID 29719593, 2018). "This minireview describes the recent updates about the deregulation mechanisms of the KEAP1/NRF2 pathway, with a particular focus on the epigenetic modulation of KEAP1 and NFE2L2 and their cellular significance and potential impact on cancer patient management." (PMID 29643973, 2018). "As in other cancer types, MALAT1 was found to interact with the methyltransferase EZH2 also in MM cells, and both MALAT1 and EZH2 inhibitors reduced H3K27Me3 at KEAP1 promoter, thus upregulating KEAP1 mRNA." (PMID 29487387, 2018). "We observed that 100 μM DMF significantly decreased KEAP1 protein expressions in primary, established cancer cell lines and in at least one of the two non-tumorigenic cell lines." (PMID 29507676, 2018). "The addition of WDR23 increases cellular sensitivity to cytotoxic chemotherapeutic drugs and suppresses NRF2 in KEAP1-negative cancer cell lines." (PMID 28453520, 2017). "KLHL9 has not been implicated in cancer, but highly homologous members of the KLHL family have such as KEAP1 and KLHL20 – both of which are notable tumour suppressors." (PMID 26781748, 2016). "The disruption of this partnership involving the ubiquitination of NFE2L2 through the KEAP1/CUL3/RBX1 complex and its posterior proteasomal degradation, which leads to the constitutive activation of antioxidant response genes is known in several cancer types." (PMID 26792175, 2016). "Investigations demonstrated that KEAP1 plays a key role in regulating apoptosis via modulation of the cellular redox balance by targeting NRF2, a transcription factor that is often overexpressed in many human cancers, for proteasome-mediated degradation." (PMID 27030985, 2016). "KEAP1 was not considered in our initial screen due to absence in the Cancer Gene Census38, providing an opportunity to further test NFE2L2 responsiveness." (PMID 28959951, 2016). "Given the relationship between KEAP1, IKKβ, BCL2, and cancer, we investigated whether the tumor cell lines with high basal NRF2 activity also had elevated IKKβ and BCL2 protein levels." (PMID 26301506, 2015). "Decreased KEAP1 expression releases the block on the transcriptional activity of NRF2, resulting in increased expression of oxidative stress enzymes and proteins that favor cancer cells survival and proliferation." (PMID 23676014, 2013). "Similar to the case of the KEAP1/NRF2 pathway, activation of HSF1 commonly occurs in cancer." (PMID 24278719, 2012).
cancer (continued). "KEAP1, MCM3, and NRF2 interactions seem to be part of some complex regulatory mechanisms, and those interactions could be exploited in cancer therapy and perhaps against altered MCM3 to inhibit NRF2 function or DNA replication process by this protein in cancers." (PMID 39941813, 2025). "Nevertheless, in tumor cells, Keap1 inactivation leads to an increase in the stability and activity of NRF2, subsequently activating numerous target genes involved in GPX4–GSH-mediated ferroptosis defense, including SLC7A11, thereby facilitating the protection of cancer cells from ferroptosis." (PMID 40136417, 2025). "Given that CDDO-Me induces an anti-tumor macrophage phenotype regardless of the cancer genotype in vitro, we sought to determine whether KEAP1 KO tumors respond to CDDO-Me treatment in vivo." (PMID 41462606, 2025). "Notably, the upregulation of these anti-cancer pathways is independent of the cancer mutation status, as this phenotype was observed in both WT CM/CDDO-Me- and KEAP1 KO CM/CDDO-Me-treated macrophages." (PMID 41462606, 2025). "In addition, we analyzed KEAP1 expression in pancarcinoma, and found that KEAP1 expression was elevated in most cancers in both non-paired samples and paired samples except in KICH compared with paired normal tissues." (PMID 38938386, 2024). "Additionally, while NQO1:CAT was not directly measured, inhibition of catalase and GSH did not lead to sensitization of KEAP1-mutated NSCLC during β-lapachone treatment, while inhibition of TXNRD and SOD1 sensitized cancers." (PMID 36978989, 2023). "Keap1/Nrf2/ARE is an important signaling pathway to react OS, regulates the transcription of many antioxidants, activates a series of defense systems, and blocks or reverses cancer occurrence by inhibiting the activation of carcinogens or inducing the detoxification of phase II metabolic enzymes." (PMID 37810967, 2023). "In addition, POLD1 knockdown in ccRCC cells significantly decreased the levels of autophagy and ferroptosis signaling pathway-related genes, including p62, NRF2, Keap1 and GPX4, which were reported to serve as the vital regulatory factors in many types of cancers." (PMID 37047824, 2023). "Targeting the SIRT6/Keap1/Nrf2/GPX4 signaling pathway facilitates ferroptosis in cancer cells, and this property may be may be one of the potential strategies to address the resistance of cancer cells to sorafenib." (PMID 35847022, 2022). "Compared with non-small cell lung cancer, KEAP1 and BRD4 expression were much higher in SCLC cells than in NSCLC cells based on publicly available RNA-seq data from Cancer Cell Line Encyclopedia (CCLE) and microarray data from Genomics of Drug Sensitivity in Cancer (GDSC)." (PMID 35453346, 2022). "Therefore, the current data regarding the upstream regulation of NRF2 in A549 cells are not applicable to cancer cells that carry a functional Keap1." (PMID 33441543, 2021). "The impact of MnPs on the Keap1/Nrf2 pathway in cancer has not yet been studied." (PMID 33815656, 2021). "However, limited studies have shown the role of Nrf2/Keap1 in the regulation of cell motility and EMT in cancer cells and hence, it remains unclear." (PMID 33441941, 2021). "Also, in the human colorectal HCT116 cancer cell line, nitric oxide, which is produced during inflammation, has been shown to lead to nuclear accumulation of NRF2, potentially through modification of key reactive cysteine residues in KEAP1." (PMID 33276631, 2020). "This study suggests that the cancer-protective effect of the KEAP1/NRF2 system is non-redundant." (PMID 32823937, 2020). "Based on studies demonstrating that sole overexpression of NRF2 in normal cells does not cause carcinogenesis, it is clear that constitutive activation of NRF2 by KEAP1 or NRF2 mutations, which are often encountered in NRF2-activated cancers, is not by itself cancer driver." (PMID 33219226, 2020).